ACAN (aggrecan)
Diseases named in the same sentence as ACAN in open-access papers (continued):
Sharing a sentence is not in itself a finding about the gene and the disease.
infection (6 papers, 2014 to 2024). The state of being infected such as from the introduction of a foreign agent such as serum, vaccine, antigenic substance or organism. "In this study, using a model of ZIKV neonatal infection, we showed that the development of PNNs is disrupted by infection resulting in a marked reduction in PNN density that is associated with an increase in cleaved forms of aggrecan and brevican." (PMID 37496706, 2023). "During acute infection and while the proinflammatory cytokines were elevated, the staining intensity of WFA remained low and the cleaved forms of aggrecan and brevican were elevated suggesting increased degradation during infection and inflammation." (PMID 37496706, 2023). "A significant increase in aggrecan neoepitope generation was detected by Elisa assay in the culture supernatant of normal rat chondrocytes by infection of Lv-Sdc4 compared with Lv-con335." (PMID 36414669, 2022). "Furthermore, the up‐regulation of protein levels of SOX9, collagen II and aggrecan in the H19‐overexpressing cells was rescued following Lenti‐miR‐29b‐3p infection." (PMID 33058414, 2020). "For molecular detection, CircZSWIM6 infection enhanced the expression of senescence markers p16 and p21, SASPs such as CXCL1 and IL‐6, decreasing aggrecan‐positive ECM components." (PMID 36604982, 2023). "We found that when SDC4 was overexpressed in normal rat chondrocytes by infection of Lv-Sdc4, the expression of COL2A1 and ACAN were decreased significantly, the expression of MMP3 was increased, both in mRNA and protein levels." (PMID 36414669, 2022). "Additionally, RNA-Seq showed that PRV inoculation during the early stage of infection led to an increase in the transcription/expression of several cellular receptors [e.g., ICAM5, ICAM2, ACAN, and DSCAM] that are known to facilitate bacterial adherence." (PMID 39041808, 2024).
bone disorder (4 papers, 2018 to 2024). "Different phenotypes were caused by different types of variants in ACAN gene known as Aggrecan- related bone disorders." (PMID 38494255, 2024). "Due to the fact that ACAN is the primary proteoglycan component of the extracellular matrix of cartilage growth plate and other cartilaginous tissues, ACAN variants were also found to be associated with genetic skeletal diseases in other species like chicken, mouse, human and horse." (PMID 30305023, 2018). "Aggrecan abnormalities result in defect in chondrocyte differentiation and endochondral ossification at the growth plate leading to a large heterogenous group of skeletal diseases." (PMID 38494255, 2024).
benign tumors (2 papers, 2020 to 2023). "When comparing the two subgroups of benign tumors, CYP11B1 and StAR were the steroidogenic proteins that were most differentially expressed in ACAn and ACAc, with lower levels of both proteins found in non-functioning ACA." (PMID 32751564, 2020).
cardiovascular disease (2 papers, 2021). "Our data clearly show that ACAN concentrations were significantly increased in plasma of ATAAD patients compared to plasma samples of healthy individuals and patients suffering from different cardiovascular disease." (PMID 33990642, 2021).
genetic diseases (2 papers, 2016 to 2022). "To date, eight human genetic diseases involving defects in aggrecan, now coined the aggrecanopathies have been identified, but the impact of these aggrecan defects on signaling in humans has not yet been fully explored." (PMID 35465334, 2022).
heart disease (1 paper, 2019). "A number of studies have proposed the contribution of versican in ECM remodeling and heart disease, but the role of aggrecan (a cartilage proteoglycan with potential role in vascular stiffness), neurocan (specific to neuronal tissue), and brevican in heart disease remains unexplored." (PMID 31547598, 2019).
ACAN also shares sentences with these, for which no sentence is quoted: spondyloepiphyseal dysplasia, Kimberley type (4 papers); aortic aneurysm (3); dysplasia (3); connective tissue disorder (2); depression (2); metabolic syndrome (2); multiple epiphyseal dysplasia (2); osteoporosis (2); 3-M syndrome (1); acromelic dysplasia (1); acute myocardial infarction (1); adenocarcinoma (1); amyloid (1); asthma (1); atopic asthma (1); attention deficit-hyperactivity disorder (1); autism (1); autism spectrum disorder (1); brain disorder (1); bulldog syndromes (1); Cachexia (1); central precocious puberty (1); Cerebellofaciodental Syndrome (1); chronic gastritis (1); congenital adrenal hyperplasia (1); cortical atrophy (1); degenerative diseases (1); dementia (1); Desbuquois Dysplasia Type 1 (1); DICER1 syndrome (1).
A further 46 diseases each share a sentence with ACAN in 1 paper.